KCTD1 (potassium channel tetramerization domain containing 1)
Description:
Is a regulator of different signaling pathways. Up-regulates ADCY5 thereby enhancing cAMP signaling, and is involved in the negative regulation of Wnt canonical, Hh and Notch signaling. Is a repressor of transcriptional activation mediated by AP-2 family members, including TFAP2A, TFAP2B and TFAP2C to various extent.
Synonyms: C18orf5; DNRD; RMDA
Tractability: PROTAC: UniProt records ubiquitination sites on it.
Gene: Protein-coding gene on chromosome 18 (26,454,910 to 26,657,401, reverse strand). Ensembl gene ENSG00000134504.
Subcellular location: Nucleus
Subcellular location (Human Protein Atlas): Nucleoplasm; Centriolar satellite; Cytokinetic bridge; Nucleoli
Pathways (Reactome):
Gene expression (Transcription): Negative regulation of activity of TFAP2 (AP-2) family transcription factors
Gene Ontology:
Molecular function: identical protein binding; protein binding; transcription corepressor activity; transcription factor binding
Biological process: negative regulation of canonical Wnt signaling pathway; negative regulation of DNA-templated transcription; negative regulation of Notch signaling pathway; negative regulation of smoothened signaling pathway; protein homooligomerization
Cellular component: nucleus; nucleoplasm
Genetic constraint (gnomAD): Loss-of-function variants: 24 observed, 55.73 expected, observed/expected ratio (o/e) 0.43, 90% interval 0.31 to 0.61. The upper end of that interval is the gene's LOEUF score, 0.61, which puts it in group 2 of 6, group 1 being the genes least tolerant of losing a copy. Missense variants: 943 observed, 1,108.4 expected, observed/expected ratio (o/e) 0.85, 90% interval 0.81 to 0.9. Synonymous variants: 511 observed, 469.48 expected, observed/expected ratio (o/e) 1.09, 90% interval 1.01 to 1.17.
Homologues: Orthologues: chimpanzee KCTD1 (99% identical), macaque KCTD1 (99% identical), pig KCTD1 (99% identical), dog KCTD1 (99% identical), mouse Kctd1 (97% identical), rat Kctd1 (97% identical), tropical clawed frog kctd1 (76% identical), zebrafish kctd1 (25% identical), Drosophila melanogaster twz (18% identical), Caenorhabditis elegans F32B4.5 (5% identical). Paralogues in human: KCTD15 (25% identical), KCTD19 (10% identical), KCTD8 (8% identical), KCTD16 (8% identical), KCTD6 (8% identical), KCTD12 (8% identical), KCNRG (7% identical), KCTD21 (7% identical), KCTD7 (7% identical), KCTD11 (7% identical), KCTD18 (6% identical), KCTD4 (6% identical), and 1 more.
Diseases named in the same sentence as KCTD1 in open-access papers:
KCTD1 is named in the same sentence as 27 diseases in open-access papers, as found by Europe PMC text mining. Sharing a sentence is not in itself a finding about the gene and the disease. The quoted sentences say what the papers report.
scalp-ear-nipple syndrome (7 papers, 2015 to 2024). Scalp-ear-nipple syndrome is characterized by the following triad: areas of hairless raw skin over the scalp (present at birth and healing during childhood), prominent, hypoplastic ears with almost absent pinnae, and bilateral amastia. "Heterozygous missense variants in the closely related paralogue KCTD1 cause scalp-ear-nipple syndrome." (PMID 38296633, 2024). "This is in contrast with all previously reported variants in KCTD1 associated with Scalp-Ear-Nipple syndrome, which reside in the N-terminal disordered region or in the BTB domain, suggesting a possible genotype–phenotype correlation." (PMID 38791218, 2024). "To date, thirteen genetic variants in KCTD1, all of which impact the N-terminus of the protein, have been reported to be associated with Scalp-Ear-Nipple syndrome." (PMID 38791218, 2024). "Mutations in KCTD1 cause developmental abnormalities and kidney fibrosis in scalp-ear-nipple syndrome." (PMID 39191250, 2024). "Several missense variants in KCTD1 have been reported to cause scalp-ear-nipple syndrome in an autosomal dominant pattern." (PMID 37485353, 2023). "In humans, heterozygous KCTD1 missense mutations occur in the scalp-ear-nipple (SEN) syndrome (OMIM 181270) or Finlay-Marks syndrome, which is a rare autosomal dominant disorder." (PMID 28818080, 2017). "In humans affected by the SEN syndrome, all heterozygous KCTD1 missense mutations were identified in the BTB domain." (PMID 28818080, 2017). "As the first mouse line harbouring a Kctd1 mutation, phenotypic analysis of Kctd1I27N heterozygous mutants at the age of 9–21 weeks revealed no visible alterations of the external physical appearance as observed in the human SEN syndrome." (PMID 28818080, 2017). "Interestingly, mutations in KCTD1 have been linked to Scalp-Ear-Nipple syndrome, which is a rare, autosomal-dominant disorder characterized by cutis aplasia of the scalp as well as minor anomalies of the external ears, digits, nails, and malformations of the breast." (PMID 31990937, 2020).
breast carcinoma (2 papers, 2023 to 2024). "Using the CRISPR/CAS9 protocol that we recently developed for knocking down the related protein, KCTD15, in breast cancer cells showed that the KCTD1 gene was downregulated in SW480 cells." (PMID 36979172, 2023). "Given its predicted function in cell proliferation, the absence of off-target effects, and genetic evidence of its role in breast cancer, we decided to prioritise lncRNA XLOC112072 (hereafter named KILR;KCTD1 Intronic LncRNA) for functional studies." (PMID 38745269, 2024). "To address this, we used a Tet-On inducible lentiviral overexpression system to overexpress KCTD1-5 or KILR, and showed that individual overexpression of KILR but not KCTD1-5 promoted apoptosis, again only in the breast cancer cell lines but not normal breast cells." (PMID 38745269, 2024).
sudden cardiac arrest (2 papers, 2011 to 2017). Unexpected rapid natural death due to cardiovascular collapse within one hour of initial symptoms. "In addition, KCTD1 has been associated in genome-wide association studies (GWAS) with sudden cardiac arrest due to ventricular tachycardia or ventricular fibrillation in patients with coronary artery disease." (PMID 28818080, 2017). "In addition, KCTD1 has been associated with sudden cardiac arrest." (PMID 28818080, 2017).
acute lymphoblastic leukemia (1 paper, 2023). Leukemia with an acute onset, characterized by the presence of lymphoblasts in the bone marrow and the peripheral blood. "Thus, among all the KCTDs examined, only two pairs of them seem to be able to discriminate not only between the ALL subtype and the relative healthy counterpart, but also between the two types of acute lymphoblastic leukemia: KCTD12 and KCTD3 for B-ALL, and KCTD1 and KCTD11 for T-ALL." (PMID 37297863, 2023).
cervix tumor (1 paper, 2021).
colon adenocarcinoma (1 paper, 2023). "Here, we re-assessed the role of KCTD1 in the WNT/β-catenin pathway by using CRISPR/CAS9 technology to knockdown the protein in the human colon adenocarcinoma cell line, SW480." (PMID 36979172, 2023). "In particular, by knocking down KCTD1 in the human colon adenocarcinoma cell line, SW480, using CRISPR/CAS9 technology, we re-assessed its ability to downregulate β-catenin, a central actor in the WNT/β-catenin signalling pathway." (PMID 36979172, 2023). "We explored the role of KCTD1 in colorectal cancer by knocking down this protein in the human colon adenocarcinoma cell line, SW480." (PMID 36979172, 2023). "The ability of KCTD1 to deregulate the action of β-catenin was confirmed in CACO2 cells, another colon adenocarcinoma cell line." (PMID 36979172, 2023).
Colon Cancer (1 paper, 2023). "Here, we show that KCTD1 has an active role in modulating the stemness and mobility of colon cancer cell lines by affecting the WNT/β-catenin signalling pathway." (PMID 36979172, 2023). "To validate and expand the results obtained using SW480 cells, we overexpressed KCTD1 in another colon cancer cell line, CACO2, which expresses lower levels of KCTD1 compared with SW480 cells (data not shown)." (PMID 36979172, 2023).
colorectal cancer (1 paper, 2023). A primary or metastatic malignant neoplasm that affects the colon or rectum. "Moreover, interrogation of the TCGA database indicates that KCTD1 downregulation is associated with β-catenin overexpression in colorectal cancer patients." (PMID 36979172, 2023). "Collectively, these findings provide clear support for the role of KCTD1 as an oncosuppressor in colorectal cancer." (PMID 36979172, 2023). "The similar effects produced on colorectal cancer cell lines by KCTD1 and KCTD12 suggest novel, previously unreported analogous activities among members of the KCTD protein family." (PMID 36979172, 2023). "Interestingly, the evaluation of the expression levels of KCTD12 and KCTD15—which are related to KCTD1—in colorectal cancer using TCGA data highlights similar downregulation." (PMID 36979172, 2023). "In this study, we explored the potential role of KCTD1 in colorectal cancer." (PMID 36979172, 2023). "Although the precise mechanism underlying β-catenin downregulation by KCTD1 has not been fully assessed, the present finding highlights the possibility of exploring new diagnostic and therapeutic strategies for colorectal cancer." (PMID 36979172, 2023). "It is worth noting that similar effects on colorectal cancer cells are induced by the misregulation of KCTD12, a protein that is distantly related to KCTD1." (PMID 36979172, 2023). "A potential link between the ability of KCTD1 to downregulate the WNT/β-catenin pathway in these cells and colorectal cancer progression was investigated by interrogating The Cancer Genome Atlas (TCGA) database." (PMID 36979172, 2023). "It is worth noting that similar effects are induced on colorectal cancer cells by the misregulation of KCTD12, a protein that is distantly related to KCTD1." (PMID 36979172, 2023). "The interplay between KCTD1 and β-catenin was also demonstrated by overexpressing KCTD1 in CACO2 colorectal cancer cells." (PMID 36979172, 2023). "Moreover, the similarities in the effects of KCTD1 and KCTD12 on colorectal cancer cell lines suggests novel, previously unreported similarities in the activities of members of the KCTD protein family." (PMID 36979172, 2023).
cyst (1 paper, 2022). A sac-like closed membranous structure that may be empty or contain fluid or amorphous material. "Reducing β-catenin hyperactivation in KCTD1 mutants through heterozygosity for the β-catenin gene Ctnnb1 attenuated mTOR hyperactivation and partially rescued the renal fibrosis and cyst formation phenotype in these mice." (PMID 35468900, 2022). "Lack of KCTD1 resulted in β-catenin and mTOR hyperactivation, associated with increased expression of TGF-β1, and led to progressive renal fibrosis and cyst formation." (PMID 35468900, 2022).
epilepsy (1 paper, 2020). A brain disorder characterized by episodes of abnormally increased neuronal discharge resulting in transient episodes of sensory or motor neurological dysfunction, or psychic dysfunction. "In a recent GWAS for epilepsy susceptibility SNPs in the KCTD1 gene reached p-values as low as 0.0003758." (PMID 31990937, 2020). "Furthermore, KCTD1 is a potassium channel gene and various members of the potassium channel gene family have been linked as causes of epilepsy." (PMID 31990937, 2020).
Insulin resistance (1 paper, 2023). Increased resistance towards insulin, that is, diminished effectiveness of insulin in reducing blood glucose levels. "Similarly, the genetic polymorphisms in different genes such as CAMK2, IGF1, IRS1, GCKR, PPARG, GCK1, and KCTD1 are found associated with insulin resistance and T2DM." (PMID 37829557, 2023).
leukemia (1 paper, 2023). A malignant (clonal) hematologic disorder, involving hematopoietic stem cells and characterized by the presence of primitive or atypical myeloid or lymphoid cells in the bone marrow and the blood. "On the other hand, the transcriptomic analysis of T-ALL patients highlighted KCTD1, KCTD9, KCTD11, and KCTD15 to be upregulated in pediatric leukemia patients." (PMID 37297863, 2023).
mental retardation (1 paper, 2011). "The other genes are potassium channel tetramerization domain containing 1 (KCTD1), zinc finger, myeloproliferative and mental retardation type 2 (ZMYM2)/zinc finger protein 198 (ZNF198), ZMYM3/ZNF261, ZMYM4/ZNF262 and glutamine-rich protein 1 (QRICH1)." (PMID 22011512, 2011).
prion disease (1 paper, 2013). A transmissible disease that is caused by a protein that is able to induce abnormal folding of normal cellular proteins, leading to characteristic spongiform brain changes, which are associated with neuronal loss without an inflammatory response. "We also hypothesize that KCTD1 mediate prion protein into ubiquitination signal pathway, and deregulation of the KCTD1 mediated prion protein ubiquitination might be both a cause and result of prion disease." (PMID 24268103, 2013).
rectum adenocarcinoma (1 paper, 2023). An adenocarcinoma arising from the rectum. "This experimental scenario coupled with the observation here reported of the downregulation and upregulation of KCTD1 and β-catenin expression, respectively, in patients with colon and rectum adenocarcinoma is suggestive of the role of KCTD1 as a potential oncosuppressor in these types of cancers." (PMID 36979172, 2023).
renal fibrosis (1 paper, 2022). A final common manifestation of a wide variety of chronic kidney diseases characterized by glomerulosclerosis and tubulointerstitial fibrosis. "Consistent with β-catenin hyperactivation being profibrotic and leading to renal fibrosis in mice lacking KCTD1 activity, kidneys of aged Aqp2Cre+Tfap2afl/fl mice that had no significant increase in active β-catenin levels did also not develop renal fibrosis." (PMID 35468900, 2022). "Our previous work showed that AP-2β induces expression of KCTD1 that functions as a repressor of β-catenin signaling and that mice lacking KCTD1 develop progressive DCT defects and renal fibrosis accompanied by β-catenin hyperactivation and downstream profibrogenic mTOR activation." (PMID 35468900, 2022).
T-cell leukemia (1 paper, 2023). A malignant disease of the T-lymphocytes in the bone marrow, thymus, and/or blood. "KCTD1 gene expression levels are significantly higher in T-cell leukemias compared with B-cell leukemias and healthy subjects." (PMID 37297863, 2023).
cancer (9 papers, 2015 to 2025). A tumor composed of atypical neoplastic, often pleomorphic cells that invade other tissues. "The potassium channel tetramerization domain-containing 1 (KCTD1) protein has been associated with cancer, whereas pathogenic variants give rise to dental anomalies and aplasia cutis." (PMID 41086914, 2025). "The role of KCTD1 as an oncosuppressor in this cancer was sustained by other important alterations induced by protein knockdown in SW480 cells." (PMID 36979172, 2023). "We also found a large number of genes functioning in the plasma membrane; four genes CHRNA3, CLIC1, KCTD1 and KCNMA1 were discovered in iron channel complex; except KCTD1, all others were associated with cancer." (PMID 26367387, 2015). "The roles of LAMC3 and KCTD1 are essential in the development and differentiation of the nervous system, while recent studies on its involvement in carcinoma have yet to be sufficient." (PMID 40584831, 2025). "We induced KILR and KCTD1-5 expression in one normal (MCF10A) and two cancer (MCF7s and Hs578T) breast cell lines, by targeting CRISPRa to their shared promoter and observed significantly suppressed cell proliferation in all three cell lines." (PMID 38745269, 2024). "However, unlike KCTD15, it has been shown that KCTD1 is involved in proteasomal degradation processes, by complexing with other E3-ubiquitine ligases, through which it participates in negative regulation of pathways which are aberrantly activated in many human cancers." (PMID 34001146, 2021). "Although KCTD1 shares several features and biological functions with KCTD15, including the inability to bind to Cul3, its role in cancer has still not been intensively investigated." (PMID 34001146, 2021).
tumor (4 papers, 2017 to 2026). "In a murine intrahepatic tumor model, KCTD1 knockdown synergizes with anti-PD-1 therapy, resulting in enhanced tumor infiltration by CD4+ and CD8+ T lymphocytes and improved anti-tumor efficacy." (PMID 41765960, 2026). "We identified FGFR2::BICC1 fusions in two tumours, and FGFR2::KCTD1 and TMEM106B::ROS1 as novel fusions with potential therapeutic implications in iCCA and confirmed oncogenic properties of TMEM106B::ROS1 in vitro." (PMID 38877653, 2024).
bone disorder (1 paper, 2024). "Dysregulation of BMP signaling similarly can lead to various bone disorders, including abnormal bone mass, and might contribute to the formation of the tori in our patients with KCTD1 variants." (PMID 38791218, 2024).
KCTD1 also shares sentences with these, for which no sentence is quoted: anhidrosis (1 paper); cardiovascular disease (1); colorectal adenocarcinoma (1); gastric cancer (1); hepatocellular carcinoma (1); medulloblastoma (1); prostate tumors (1).